CELA2A (chymotrypsin like elastase 2A)
Description:
Elastase that enhances insulin signaling and might have a physiologic role in cellular glucose metabolism. Circulates in plasma and reduces platelet hyperactivation, triggers both insulin secretion and degradation, and increases insulin sensitivity.
Synonyms: ELA2A; AOMS4; PE-1
Tractability: Antibody: UniProt places it where antibodies can reach, with high confidence; its Gene Ontology location is reachable by antibodies, with high confidence; UniProt predicts a signal peptide or a membrane-spanning region.
Gene: Protein-coding gene on chromosome 1 (15,456,728 to 15,472,091, forward strand). Ensembl gene ENSG00000142615.
Subcellular location: Secreted
Pathways (Reactome):
Developmental Biology: Developmental Lineage of Pancreatic Acinar Cells; Formation of the cornified envelope
Gene Ontology:
Molecular function: endopeptidase activity; protein binding; serine hydrolase activity; serine-type endopeptidase activity
Biological process: insulin catabolic process; regulation of insulin secretion; regulation of platelet aggregation; response to insulin; proteolysis
Cellular component: extracellular region; keratohyalin granule; cytosol
Genetic constraint (gnomAD): Loss-of-function variants: 34 observed, 38.99 expected, observed/expected ratio (o/e) 0.87, 90% interval 0.66 to 1.16. The upper end of that interval is the gene's LOEUF score, 1.16, which puts it in group 5 of 6, group 1 being the genes least tolerant of losing a copy. Missense variants: 330 observed, 362.16 expected, observed/expected ratio (o/e) 0.91, 90% interval 0.83 to 1. Synonymous variants: 150 observed, 154.39 expected, observed/expected ratio (o/e) 0.97, 90% interval 0.85 to 1.11.
Homologues: Orthologues: chimpanzee CELA2A (99% identical), pig CELA2A (81% identical), rat Cela2a (79% identical), mouse Cela2a (75% identical), zebrafish ela2l (66% identical), zebrafish ela2 (64% identical), tropical clawed frog cela2a (62% identical). Paralogues in human: CELA2B (88% identical), CELA3B (58% identical), CELA3A (58% identical), CELA1 (53% identical), PRTN3 (35% identical), ELANE (33% identical).
Diseases named in the same sentence as CELA2A in open-access papers:
CELA2A is named in the same sentence as 18 diseases in open-access papers, as found by Europe PMC text mining. Sharing a sentence is not in itself a finding about the gene and the disease. The quoted sentences say what the papers report.
Hyperglycemia (2 papers, 2020 to 2022). An increased concentration of glucose in the blood. "In the presence of CELA2A gene mutations and therefore nonfunctional CELA2A protein, dysregulated insulin secretion, hyperglycemia, and the eventual onset of T2D results." (PMID 35769082, 2022).
Obesity (2 papers, 2024 to 2026). Accumulation of substantial excess body fat. "Chymotrypsin-like elastase family member 2A (CELA2A), a circulating pancreatic serine protease implicated in metabolic regulation, has been proposed to contribute to these effects, although its regulation in obesity and after metabolic surgery remains unclear." (PMID 42267294, 2026).
colitis (1 paper, 2021). Inflammation of the colon. "Transcription level of Cela2A mRNA was higher in colitis condition compared to control mice." (PMID 33674762, 2021).
cystic fibrosis (1 paper, 2022). Autosomal recessive disorder caused by pathogenic variants in the CFTR gene (cystic fibrosis transmembrane conductance regulator), which encodes a chloride and bicarbonate channel expressed in epithelial cells, and follow the diagnosis criteria. "These include hereditary pancreatitis induced by mutations in PRSS1, metabolic syndrome caused by mutations in CELA2A, Cystic Fibrosis, and Wolcott-Rallison Syndrome." (PMID 35769082, 2022).
diabetic retinopathy (1 paper, 2017). "Overall, the network effects of CASP9, CELA2A, CELA2B and DANJC16 on type 2 diabetes, especially diabetic retinopathy, worth further investigations." (PMID 28511641, 2017).
Hypertension (1 paper, 2024). The presence of chronic increased pressure in the systemic arterial system. "Among the genetic factors linked to metabolic syndrome, rare variants in the CELA2A gene have been identified as associated with all its traits, including hypertension." (PMID 38691164, 2024).
idiopathic hypertension (1 paper, 2024). "Common variants of pancreatic exocrine chymotrypsin-like elastase 2A (CELA2A) are associated with idiopathic hypertension." (PMID 38691164, 2024).
infection (1 paper, 2025). The state of being infected such as from the introduction of a foreign agent such as serum, vaccine, antigenic substance or organism. "Conversely, the most significantly downregulated proteins, including PXN (p = 0.0127) and CELA2A (p = 0.0469), were linked to cell adhesion, migration, and metabolic regulation, suggesting a decline in cellular activity and metabolic demand during infection." (PMID 40429216, 2025).
metabolic disease (1 paper, 2025). A congenital disorder (due to inherited enzyme abnormality) or acquired (due to failure of a metabolically important organ) disorder resulting from an abnormal metabolic process. "A mutated or downregulated expression of CELA2A may therefore affect insulin secretion/degradation/sensitivity and can be considered important for metabolic disease." (PMID 40652086, 2025).
CELA2A also shares sentences with these, for which no sentence is quoted: atherosclerosis (2 papers); pancreatic carcinoma (2); cancer (1); cholangiocarcinoma (1); hypertriglyceridemia (1); Impaired glucose tolerance (1); metabolic syndrome (1); tumor (1); type 2 diabetes (1).